NKX2-1 (NK2 homeobox 1)
Diseases named in the same sentence as NKX2-1 in open-access papers (continued):
Sharing a sentence is not in itself a finding about the gene and the disease.
tumor (197 papers, 2005 to 2026). "We demonstrate here that tumor development and progression markedly differ in lung and thyroid targeted by Braf mutation in Nkx2.1CreERT2 mice heterozygous for Nkx2-1." (PMID 37534159, 2023). "Accordingly, NKX2–1 tumour-bearing mice display enhanced tumour aggressiveness associated with systemic metabolic rewiring." (PMID 36932191, 2023). "Although tumor cells re-expressed Nkx2-1 in more advanced tumor stages, it is thus possible that monoallelic loss of Nkx2-1 influences differently BRAF mutant lung and thyroid cells during early tumor development." (PMID 37534159, 2023). "Three weeks post-tumor initiation, mice were injected with corn oil (as vehicle control) or with tamoxifen to recombine LoxP-sites within Nkx2-1 alleles by CreERT2 recombinase." (PMID 33821796, 2021). "And NK2 homeobox 1(NKX2‐1) which was associated with tumor progression in LUSC was identified as a target gene of miR‐338." (PMID 32965722, 2021). "In a KrasG12D-mutant LUAD GEMM, Nkx2-1 deletion enhances tumor growth and causes pulmonary to gastric transdifferentiation, which is driven by the transcription factors FoxA1 and FoxA2." (PMID 33821796, 2021). "But it was unclear how IMA tumor cells that developed from a mutation in the BRAF gene are affected by this loss in NKX2-1, and how transitioning to a different cell type impacts their response to treatment." (PMID 33821796, 2021). "Of these prognostic factors, only NKX2-1, thought to be a tumor suppressor, was previously associated with LADC prognosis." (PMID 29069744, 2017). "Data specifically link Nkx2-1 downregulation to loss of differentiation, enhanced tumor seeding ability and increased metastatic proclivity." (PMID 22952714, 2012). "Interestingly, we found that the tumor mutational burden correlated negatively with NKX2-1 expression." (PMID 38708353, 2024). "Loss of NKX2-1 could lead to the recruitment of tumor-associated neutrophils which promote the proliferation of lung squamous cell, and high expression of ARNTL2, which could drive metastatic self-sufficiency and predict poor prognosis for LUAD patients." (PMID 35938013, 2022). "Thus, in this model, loss of NKX2-1 is compatible with tumor progression to a high-grade state, despite its impairment of tumor initiation." (PMID 33821796, 2021). "Importantly, several of these distinguishing features observed in vivo, such as the association between low NKX2-1 and high pERK levels are conserved in vitro in primary tumor spheroid cultures from autochthonous BP and BPN tumors." (PMID 33821796, 2021). "Low expression of NKX2-1 leads to loss of differentiation and enhanced tumor seeding ability." (PMID 32822576, 2020). "Moreover, concomitant loss of NKX2-1 and FoxA1/2 activity at tumor initiation leads to a distinct differentiation state characterized by expression of multiple markers of the transitional epithelium normally found at the SCJ of the GI tract." (PMID 30475207, 2018). "In addition, several studies observed frequent NKX2-1 mutations in IMA, and proposed NKX2-1 as a lineage-specific tumor suppressor in the lung." (PMID 30513627, 2018). "The underlying mechanism of NKX2–1 as a tumor suppressor is not fully understood but we speculated that it might be linked to its associated miRNAs, miR-365 and miR-33a." (PMID 29237428, 2017). "Here, we addressed this issue by monitoring and comparing tumor prevalence and tumor features correlated with the actual number of cells carrying an activated Braf mutant allele, primarily targeted to thyroid and lung by the Nkx2-1 promoter, in Nkx2.1-CreERT2;BrafCA/+ mice." (PMID 37534159, 2023). "Furthermore, the observed proliferation upon NKX2-1 loss could provide the substrate for or synergize with additional oncogenes and tumor suppressors." (PMID 33947861, 2021).
tumor (continued). "SOX2 and NKX2‐1, as pivotal lineage‐defining TFs in lung epithelium, exert a decisive influence on the regulation of tumour cell fate." (PMID 40847555, 2025). "Mouse models with Sox2 overexpression combined with Nkx2-1 and Lkb1 loss (SNL model) demonstrated enhanced adeno-to-squamous differentiation of tumors as well as tumor-associated neutrophil (TAN) recruitment." (PMID 40327401, 2025). "In this issue of Genes & Development, Fort and colleagues (doi:10.1101/gad.352742.125) report HNF4α as a key regulator of hybrid identity states and tumor progression in NKX2-1-positive LUAD." (PMID 40707360, 2025). "Although TTF-1 or its gene NKX2-1 functions both as a lineage oncogene and a tumor suppressor, its role in the TIME has been less studied." (PMID 40824335, 2025). "IHC staining of NKX2‐1 was carried out in the excised tumor tissues to validate the expression level of NKX2‐1." (PMID 39113226, 2024). "Here, we demonstrated that LUAD tumors with NKX2‐1 depletion exhibited increased infiltration of tumor‐promoting neutrophils via the activation of CXCLs/CXCR2 signaling." (PMID 39113226, 2024). "The tumor tissue-derived epithelial cell cluster exhibited high activity of the AT2 cell marker Nkx2-1." (PMID 38531851, 2024). "We annotated these clusters with canonical cell-type markers and identified tumor cells expressing Epcam and Nkx2-1, B cells expressing Cd19, T cells expressing Cd3d, and NK cells expressing Ncr1." (PMID 39718828, 2024). "Not surprisingly, the TIMER results are consistent with our results from R software, with NKX2-1 expression found to be significantly lower in tumor than in normal tissue." (PMID 38708353, 2024). "IHC results showed NKX2-1 protein expression in tumor tissues of both LUAD and LUSC, with LUAD displaying negative, moderate, and strong expression, and LUSC showing negative, weak, and moderate expression." (PMID 38708353, 2024). "FOSB and NKX2‐1 showed significant upregulation in the CTumour group compared with the Tumour group." (PMID 39113235, 2024). "Raw RNA sequencing (RNA-seq) data of LUSC from The Cancer Genome Atlas (TCGA) were used in bioinformatics analysis to characterize NKX2-1 expression levels in tumor and normal tissues." (PMID 38708353, 2024). "In summary, our study delineated the role of NKX2‐1 as a bona fide modulator of the immune tumor microenvironment of LUAD." (PMID 39113226, 2024). "This suggests that neutrophils activated by NKX2‐1‐low cancer cells contribute to tumor progression by modulating the TME with tumor‐promoting molecules and inflammatory cells." (PMID 39113226, 2024). "Our data demonstrated the pivotal role of the CXCLs/CXCR2 signaling in NKX2‐1‐low tumor progression and cancer‐promoting neutrophil infiltration in LUAD." (PMID 39113226, 2024). "In present study, we examined and compared NKX2-1 expression between the normal and tumor tissues of several pan-cancers using TIMER data." (PMID 38708353, 2024). "This study unveils how NKX2‐1 modulates the infiltration of tumor‐promoting neutrophils by inhibiting CXCLs/CXCR2‐dependent mechanisms." (PMID 39113226, 2024). "The result showed low levels of NKX2‐1 in shNKX2‐1/LL2‐derived tumor cells when compared with the shCtrl/LL2‐derived tumor cells." (PMID 39113226, 2024). "Collectively, these findings emphasize that the CXCLs/CXCR2‐dependent mechanism is essential for tumor progression and neutrophil infiltration in NKX2‐1‐low LUAD." (PMID 39113226, 2024). "Tumor Immune Estimation Resource (TIMER) dataset was used to systematically analyze the correlation between NKX2‐1 differential expression and immune cell infiltrations." (PMID 39113226, 2024). "The inhibition of CXCR2 chemokine receptor with specific inhibitor SB225002 decreased the infiltration of tumor‐promoting neutrophils, resulting in reduced tumor growth in NKX2‐1‐low tumors." (PMID 39113226, 2024).
tumor (continued). "In the past, NKX2–1 has often been referred to as a double-edged sword, given its described role as both a tumour suppressor as well as an oncogene." (PMID 36932191, 2023). "Suggested impact of Nkx2-1 haploinsufficiency on BRAFV600E-induced tumor phenotypes relies on circumstantial evidence including observations of reduced NKX2-1 expression levels in early neoplastic lesions." (PMID 37534159, 2023). "Remarkably, 11 weeks after cancer cell injection, mice injected with NKX2–1 overexpressing A549 cells showed similar HLA staining of the lungs indicating a phenotypic switch of NKX2–1 cells in the tumour." (PMID 36932191, 2023). "Our findings identify NKX2–1 tumours as an extra subset of cancers that can benefit from the therapeutic targeting of serine/glycine synthesis hyperactivation." (PMID 36932191, 2023). "Presently, there are no other suitable Cre drivers that specifically targets Nkx2-1-lineage cells and would be instrumental to further address in vivo the potential role of Nkx2-1 gene dosage in sporadic tumor development in thyroid and lung." (PMID 37534159, 2023). "Nevertheless, PSPH mRNA expression was 1.7-fold elevated in the 50% of NEPC tumours with the highest NKX2–1 expression versus the 50% with the lowest NKX2–1 expression." (PMID 36932191, 2023). "In our study, we found that four ADC patients (P5, P10, P11, and P13) had a large proportion of tumor cells coexpressing NKX2-1 and TP63." (PMID 35962452, 2022). "For P5, the tumor areas on the section were strongly and diffusely positive for NKX2-1 and TP63, and 51% (35,654 out of 70,292 cells analyzed) of the individual cancer cells co-expressed these two markers simultaneously." (PMID 35962452, 2022). "We further checked the gene expression in primary tumor versus normal tissue for genes JAK2, PRDM16, LRP1B, NIN, and NKX2-1 with variants repeatedly enriched in variant-based analysis, and, FANCE, enriched in gene-based burden testing, using the TCGA database." (PMID 35954343, 2022). "Surprisingly, Nkx2-1 deletion in both the concomitant and sequential tumor models led to increased MAPK signaling downstream of oncogenic BRAF as assessed by IHC." (PMID 33821796, 2021). "The variable levels of Nkx2-1 and Sftpc in clusters 4–8 suggests that some of these cells represent higher grade tumor cells that stochastically lose NKX2-1 activity and expression, as has been documented in KRASG12D-driven GEMMs." (PMID 33821796, 2021). "(F) Beeswarm plots of single cell sequencing data showing expression levels of Nkx2-1, Sftpc and Aurkb transcripts in tumor clusters 1–8." (PMID 33821796, 2021). "Despite similar morphologic phenotypes in the BRAFV600E and KRASG12D models, Nkx2-1 deletion at tumor initiation had a profoundly distinct effect when combined with either of these oncogenes." (PMID 33821796, 2021). "Nkx2-1 deletion led to a lower tumor burden 8 weeks after initiation and significantly prolonged overall survival." (PMID 33821796, 2021). "SELENBP1 is a direct target for transcription factor Nkx2-1, which can inhibit tumor clonal growth and migration and inhibit malignant progression of LUAD in vivo." (PMID 34604392, 2021). "Similar to cluster 3, cluster 8 exhibited high expression of Aurkb, Plk1, and other genes that suggest that these NKX2-1-positive tumor cells are in G2/M phase." (PMID 33821796, 2021). "Of note, a small minority of tumor burden (~4% on average) was NKX2-1-positive, indicative of a low rate of incomplete recombination." (PMID 33821796, 2021). "Despite these differences, NKX2-1 targets (e.g. Sftpc) were detected at higher levels than expected in sorted BPN tumor cells." (PMID 33821796, 2021).
tumor (continued). "KrasG12D activation with concomitant Nkx2-1 deletion (KrasLSL-G12D/+; Nkx2-1F/F) together with either Foxa1 or Foxa2 disruption was reported to promote squamous differentiation of tumor lesions." (PMID 32747478, 2020). "Kaplan–Meier analyses of the top four tumor suppressor genes show that high expression of both GMIP and NKX2-1 is associated with significantly longer patient survival." (PMID 33227088, 2020). "NKX2-1 is reported to be involved in lung development, and it inhibits epithelial to mesenchymal transition, supporting its role as a tumor suppressor." (PMID 32925947, 2020). "We found that normal murine type two pneumocytes, which are the presumed cell of origin for NKX2-1-positive tumor cells, clustered with presumptive NKX2-1-positive C1 cells." (PMID 30475207, 2018). "The top-ranked variant (rs34081947) in this region showed a significant association ((additive model of linear regression) P=0.0323) with the NKX2-1 expression level in the tumour tissue." (PMID 28703219, 2017). "The rs944289 showed a greater significant association with NKX2-1 and SFTA3 expression levels compared with rs34081947 in both the tumour and normal tissues." (PMID 28703219, 2017). "Most of the studies that have examined the role of NKX2–1 in oncogenesis have highlighted its role as tumor suppressor." (PMID 29237428, 2017). "It is possible that tumor cells maintaining lung-lineage characteristics use tissue/cell specific factors including NKX2-1 to control proliferation and other functions." (PMID 22242187, 2012). "AdCa is a peripheral tumor and continues expressing proteins typical of the lung physiology such as mucins, surfactant proteins, or NKX2-1." (PMID 23028920, 2012). "Our findings point to NKX2-1 as a direct transcriptional regulator of these independent markers of lung tumorigenesis modulating their level of expression at different stages of tumor progression." (PMID 22242187, 2012). "In our study, HIF1A, similarly to NOTCH1, correlated with most of the other tumor markers but less with MUC1 or NKX2-1 as markers of lung physiology." (PMID 23028920, 2012). "The observation of very low TDS in specimen TC1088, principally attributed to loss of NKX2-1, is particularly interesting as NKX2-1 loss is correlated with de-differentiated human TC50, and may suggest that TC1088 might represent a de-differentiated tumor." (PMID 41353477, 2025). "NKX2–1 functions as a tumor suppressor in LUSC, and its deletion may promote SOX2-driven transformation by inhibiting SOX2 targeted genes, thereby accelerating the development of LUSC." (PMID 40568576, 2025). "In other words, low levels of NKX2‐1 in cancer cells may create a pro‐tumor immune microenvironment, fostering malignant tumor development." (PMID 39113226, 2024). "Additionally, immunoblotting and qRT‐PCR were also performed to validate the expression of NKX2‐1 in the excised tumor tissues." (PMID 39113226, 2024). "Moreover, the correlation between the NKX2-1 expression level and tumor mutation burden (TMB), tumor microenvironment (TME), and immune cell infiltration revealed that NKX2-1 participates in the development of LUSC." (PMID 38708353, 2024). "GSEA revealed that the downregulation of NKX2-1 was involved in tumor progression of LUSC, suggesting that it may be important for the therapeutic benefits of LUSC." (PMID 38708353, 2024). "IHC revealed NKX2-1 protein expression in tumor tissues of both LUAD and LUSC." (PMID 38708353, 2024).
tumor (continued). "An independent study showed that NKX2-1 possibly regulated the adeno-to-squamous transdifferentiation to shape the tumor microenvironment or affected immune cell types shaping the correspongding tumor microenvironment, then determined tumor phenotype." (PMID 38708353, 2024). "Having illustrated the role of CXC chemokines in mediating cell‐cell communication between tumor cells and neutrophils by scRNA‐seq analysis, we proceeded to assess the regulatory role of NKX2‐1 on CXC chemokine expression and secretion in human LUAD cell culture model." (PMID 39113226, 2024). "Next, we focused on the effects of NKX2–1 expression on in vivo tumour metabolism." (PMID 36932191, 2023). "Both lung and thyroid cells transiently downregulated NKX2-1 in early tumor stages." (PMID 37534159, 2023). "Notably, although NKX2-1 was overall strongly expressed in advanced lung tumor stages, small tumor foci presumably representing early lesions often showed a heterogeneous and overall reduced nuclear NKX2-1 immunoreactivity." (PMID 37534159, 2023). "Overall, these in vivo data together with the patient observations strongly indicate that NKX2–1 overexpression mainly contributes to cancer progression and spreading when the tumour size has become substantial and availability for nutrients such as serine and glycine is limited." (PMID 36932191, 2023). "In addition, we discovered that NKX2–1 overexpression enables cancer cells to invade and that NKX2–1 genetic alterations are enriched in metastatic sites compared to primary tumours." (PMID 36932191, 2023). "Thus, the oncogenic and inhibitory function of NKX2-1 in the same tumor type confirms its role as a bifunctional lineage factor." (PMID 36203529, 2022). "Interestingly, we detected a minor population of POU2F3-positive tumor cells in seven NKX2-1-positive cases." (PMID 33821796, 2021). "Likewise, previous reports along with these data show that reduced expression of TTF‐1 is significantly associated with unfavourable prognosis in patients with LAD, indicating a tumour suppressive function of NKX2‐1/TTF‐1 in lung tumourigenesis." (PMID 34014042, 2021). "(A minority of tumor burden ~18% on average) was NKX2-1-positive in the survival study." (PMID 33821796, 2021). "Importantly, such studies have revealed that NKX2-1 functions as a tumor promoter or a tumor suppressor in a context-dependent fashion." (PMID 33980985, 2021). "In addition, NKX2‐1/TTF‐1‐regulated microRNA‐532‐5p has a tumour suppressive role by targeting KRAS in LADs." (PMID 34014042, 2021). "MAPK inhibition in NKX2-1-negative tumor cells was also associated with induction of several markers of chemosensory tuft cells, including the lineage specifier Pou2f3 as well as Gfi1b and Gnat3." (PMID 33821796, 2021). "Previous studies mainly reported favorable prognosis with NKX2-1 expression in mixed onco-driver, tumor stages and pathological backgrounds, while our study demonstrated the predictive value of NKX2-1 copy number gain to favor adjuvant TKI treatment in a more defined population." (PMID 34750392, 2021). "A recent study elucidated the role of lung cancer lineage specifiers SOX2 and NKX2-1 in tumor cell fate and neutrophil recruitment, suggesting that the determination of tumor immune microenvironment might impact the nature of the tumor." (PMID 32351880, 2020). "Key inactivated transcriptional regulators, which are potential tumor suppressors, include NKX2-1." (PMID 32925947, 2020). "Aberrant levels of NKX2-1 in particular may target newly open chromatin regions in KPG tumor cells to activate de-novo tumor suppressive gene networks." (PMID 32157212, 2020). "At both 2 and 12 weeks p.i., the largest proportional increase driven by PIK3CAH1047R expression is seen in NKX2-1+/SFTPA- tumor cells, implying that at both early and late time points, decreased expression of NKX2-1 cannot explain the observed decrease in SFTPA expression." (PMID 31452510, 2019).